GNAQ (G protein subunit alpha q)
Diseases named in the same sentence as GNAQ in open-access papers (continued):
Sharing a sentence is not in itself a finding about the gene and the disease.
melanoma (continued). "Several genes have been identified as genetically altered drivers of melanoma tumorigenesis, such as NRAS, CDNK2A, MITF, PTEN, KIT, GNAQ, GNA11 or CTNNB1, but most (60%) melanomas have BRAF gene mutations." (PMID 35326682, 2022). "All these melanomas were wild-type for CYSLTR2 and the majority carried mutations in GNAQ, GNA11 or PLCB4." (PMID 33588787, 2021). "GNAQ and GNA11 are both G protein α subunit family members and more than 80% of uveal and blue-nevus-like melanomas were found to have activating mutations." (PMID 35008286, 2021). "Identifying GNAQ or GNA11 mutations can be useful to diagnose uveal melanoma and differentiate it from other types of melanomas and melanoma of undefined origin." (PMID 34441278, 2021). "As recently reported, potential markers in melanoma are mutations (on BRAF, NRAS, KIT, GNA11/GNAQ, NF1, CDKN2AI, immunohistochemical biomarkers (such as PD-11 and PD-L1, as well as mutated BRAF and NY-ESO-1), miRNAs, and other serum molecules." (PMID 33302400, 2020). "In this study, we examined POM for alterations in candidate melanoma driver genes (BRAF, NRAS, KRAS, GNA11, GNAQ) and genes implicated in UM prognosis (EIF1AX, SF3B1, BAP1)." (PMID 30558566, 2018). "MLPA was conducted to detect chromosomal alterations and Sanger sequencing used to identify point mutations in candidate melanoma driver genes (BRAF, NRAS, KRAS, GNA11, GNAQ), and other genes implicated in melanoma prognosis (EIF1AX, SF3B1)." (PMID 30558566, 2018). "While GNAQ and GNA11 mutations were recently reported to occur in 9.5% of mucosal melanomas, our study suggests these mutations are less frequent in this tumor entity." (PMID 28380455, 2017). "Some mutations present in melanoma, such as BRAF, NRAS, GNAQ, or GNA11, and rearrangements in fusion kinases, have been observed in benign nevi, and therefore represent events acquired early during tumor progression." (PMID 29156643, 2017). "Other gene mutations in melanoma include NRAS, GNAQ and KIT, estimated to be present in 13–25%, 1.3% (but much more in uveal melanoma) and 2–8% (but more in acral/mucosal subtypes) of melanomas respectively." (PMID 29100459, 2017). "As expected, the RAS pathway was mutated in the majority of melanomas (89%) and the MAPK pathway (GNA11 and GNAQ) in 4% of melanomas, displaying a mutually exclusive pattern with mutations in the RAS pathway (P = 0.001)." (PMID 28267273, 2017). "Approximately 75% of melanomas have known driver oncogenic mutations in BRAF, NRAS, GNA11 or GNAQ, while the mutations providing constitutive oncogenic signaling in the remaining melanomas are not known." (PMID 27273450, 2016). "Recently, genetic subsets of melanoma have been characterized, especially with known driver mutations such as BRAF, NRAS, GNAQ, RAC1, C-KIT, and others." (PMID 26871475, 2016). "We defined “pan-negative” samples as those melanomas harboring none of the well-known, specific, and recurrent mutations in the genes BRAF, NRAS, KIT, GNAQ, or GNA11, which are commonly mutated in melanoma." (PMID 25537510, 2015). "The optimum treatment for other subsets, including NRAS-, GNAQ- or GNA11-mutant melanomas, remains to be determined." (PMID 26084293, 2015). "The mutational status of BRAF, RAS, GNAQ, GNA11 and KIT genes in Grey horse melanomas was determined by direct sequencing." (PMID 25413220, 2014). "A typical example of a genomic panel recommended for cancer diagnosis is a panel comprising of BRAF, KIT, NRAS, GNA11 and GNAQ for Melanomas." (PMID 23863689, 2013). "In melanoma, Q209 resulted in constitutive activation of GNAQ leading to activation of the MAPK pathway." (PMID 24498620, 2013).
melanoma (continued). "We confirmed the previously reported cytotoxic effect of a MEK inhibitor against cell lines with BRAFV600E mutations, but in addition the cytotoxic activity was evident in a high proportion of melanoma cell lines with NRAS, GNAQ or GNA11 driver mutations." (PMID 22515704, 2012). "Directing this test to a single disease, 90 of 150 (60%) melanomas from sites throughout the body harbored a mutation tested, including 57, 23, 6, 3, and 2 mutations in BRAF, NRAS, GNAQ, KIT, and CTNNB1, respectively." (PMID 22536370, 2012). "Recent years have seen the emergence of promising therapies, including tebentafusp, which stimulates immune responses against gp100-expressing melanoma cells, and darovasertib, a potent PKC inhibitor that targets MAPK pathway activation driven by GNAQ/GNA11 mutations." (PMID 40565803, 2025). "This corroborates our findings that oncogenic GNAQ can drive neurofibroma as well as melanoma." (PMID 39804140, 2025). "Previously, ‘driver-negative’ (i.e. the absence of BRAF, NRAS, KIT, GNAQ or GNA11 mutations) melanoma cell-lines that were less sensitive to trametinib and which displayed paradoxical activation of MEK1/2, were found to show basal EGFR activation due to AREG." (PMID 35993275, 2022). "Previous studies mostly implicated its mutations in melanoma, and GNAQ mutations have not been documented in NSCLC." (PMID 33845897, 2021). "Furthermore, for mutated genes normally related to non‐sun‐induced melanomas (KIT, GNA11, GNAQ), we found that KIT and GNA11 were enriched in the triple‐wild‐type group (FDR < 0.001 or 0.01, respectively)." (PMID 28267273, 2017). "Finally, other less frequently mutated melanoma genes (KRAS, HRAS, KIT, GNAQ, GNA11) were enriched in tumors wild‐type for BRAF, NRAS, and NF1." (PMID 28267273, 2017). "Spitz tumors generally lack mutations in oncogenes classically associated with melanoma, such as NRAS, KIT, GNAQ, and GNA11, though distinct histopathologic forms have been found to harbor BRAFV600E and HRAS mutations, and suggest a role for activating kinase pathways in tumorigenesis." (PMID 28895885, 2017). "Lovly and coworkers have developed a melanoma-specific multiplex mutational profiling assay to detect the 43 recurrent mutations occurring in 6 genes frequently mutated in melanomas: BRAF, NRAS, KIT, GNAQ, and GNA11." (PMID 29156643, 2017). "Melanomas are characterized by activating “driver” mutations in BRAF, NRAS, KIT, GNAQ, and GNA11." (PMID 26084293, 2015). "Finally, sequence analysis of the exon 4 and 5 of GNAQ gene, whose mutations have been associated with wild type BRAF and NRAS melanomas, revealed wild type status in all samples." (PMID 24238212, 2013). "Among the first 150 melanomas genotyped with informed consent (from 07/08/2010 to 12/13/2010), 90 (60%) had at least one mutation, including 57, 23, 6, 3, and 2 mutations in BRAF, NRAS, GNAQ, KIT, and CTTNB1, respectively." (PMID 22536370, 2012). "We report here development, validation, and implementation of an assay designed to simultaneously detect 43 common somatic point mutations in 6 genes (BRAF, NRAS, KIT, GNAQ, GNA11, and CTNNB1) potentially relevant to existing and emerging targeted therapies specifically in melanoma." (PMID 22536370, 2012). "The literature suggests that malignant NCH may be distinct from melanoma based on the lack of GNAQ, NRAS, BRAF, and KIT mutations that are commonly identified in melanoma." (PMID 40265343, 2025). "Similarly, targeting GNAQ/11 activates the MAPK pathway which induces melanoma autophagy, resulting in therapy ineffectiveness in UM treatment, and the concomitant inhibition of Gα and autophagy increases melanoma cell death and prolongs the survival of mice bearing melanomas." (PMID 36003368, 2022). "Thus, CRAF is a bona fide alternative oncogene for BRAF/NRAS/GNAQ/GNA11 wild type melanomas." (PMID 27273450, 2016).
melanoma (continued). "However, treatment options remain limited for the patients that lack mutations in the five most commonly mutated melanoma genes (BRAF, NRAS, KIT, GNAQ and GNA11) and the prognosis of such patients is particularly pool with a median overall survival of less than 1 year." (PMID 26424083, 2015). "At least 6 genes have been shown to be recurrently mutated in melanoma, including the serine-threonine kinase encoded by BRAF; the receptor tyrosine kinase encoded by KIT; the GTP-binding proteins encoded by NRAS, GNA11, and GNAQ; and the WNT signaling pathway component encoded by CTNNB1." (PMID 22536370, 2012). "However, GNAQ or GNA11 mutations have never been reported in this type of melanoma." (PMID 39804140, 2025). "Comprehensive molecular profiling, including common melanoma-associated mutations in BRAF, NRAS and the GNAQ/GNA11 signaling pathway, was not performed in this case." (PMID 41294657, 2025). "In exceedingly difficult cases, molecular and genomic analysis can also be beneficial, as melanoma arising in blue nevi do not typically exhibit BRAF mutations, but rather GNAQ, GNA11, PLCB4, or CYSLTR2 mutations." (PMID 40843873, 2025). "The standard four-probe FISH assay should not be applied to tumors for which melanoma arising in blue nevus is a consideration because genomic CNAs typically observed in melanoma arising in blue nevus (GNAQ and GNA11) are different than those of the typical melanoma pathways." (PMID 38247727, 2024). "It has been reported, that NTRK fusions and typical oncogenic drivers, such as BRAF, NRAS, GNAQ and GNA11 are mutually exclusive and NTRK fusions might be more common in BRAF or NRAS wild-type melanomas." (PMID 35993275, 2022). "In the future, the identification of the epidermal signals that restrain the GNAQQ209L oncogene could suggest novel therapies for GNAQ and GNA11 mutant melanomas." (PMID 34939927, 2021). "Sequencing of mutation hotspots in five melanoma driver genes (BRAF, NRAS, KRAS, GNAQ, GNA11) did not reveal any changes in 9/11 patients." (PMID 30558566, 2018). "Among 253 melanomas, 129 (51.0%) BRAF, 45 (17.8%) NRAS, 6 (2.4%) KIT, 4 (1.6%) GNAQ, 2 (0.8%) GNA11, 2 (0.8%) MAP2K1 and no MAP2K2 gene mutations were detected by the biochip assay." (PMID 28881731, 2017). "In this article, we first briefly outline the function of G protein coupled receptors in cancer, and then specifically examine the roles of the seven transmembrane G protein coupled Endothelin B receptor (Ednrb) and the G proteins, GNAQ and GNA11, in both melanocyte development and melanoma." (PMID 27148356, 2016). "The present study also shows that somatic activating BRAF, RAS, GNAQ, GNA11 and KIT mutations, frequently observed in human melanomas, are not required for melanoma development in Grey horses." (PMID 25413220, 2014). "Our results indicate that GNAQ and BRAF activation drive distinct intracellular signalling pathways that may be useful for therapeutic decisions in human melanomas." (PMID 23904987, 2013). "These chromosomal regions contain genes [GNAQ (9q21.2), BRAF (7q34), PTEN (10q23.31), CCND1 (11q13.3), RREB1 (6p24.3), MYB (6q23.3), and CDKN2A (9p21.3)] involved in the MAPK pathway, which is consistent with the involvement of this pathway in the pathogenesis of melanoma." (PMID 36614156, 2022). "The underlying mechanism for the restriction of GNAQ and GNA11 mutations to non-epithelial melanomas is unknown." (PMID 34939927, 2021).
melanoma (continued). "It is possible that a better understanding of the ability of GNAQQ209L to switch from acting as an oncogene to an inhibitor of melanocyte growth could lead to new therapies for GNAQ and GNA11 mutant melanomas, which lack effective treatment options for metastatic disease." (PMID 34939927, 2021). "Hence, gain-of-function mutations in GNAQ, GNA11, or PLCB4 only drive melanoma in melanocytes surrounded by mesenchymal stromas, and not by keratinocytes." (PMID 34939927, 2021). "We found that the ERK pathway is constitutively activated in Grey horse melanoma tumours and cells in the absence of somatic oncogenic mutations in BRAF, RAS, GNAQ, GNA11 and KIT that are associated with activation of this pathway in the majority of human melanocytic tumours." (PMID 25413220, 2014). "We found that the ERK pathway is constitutively activated in Grey horse melanoma tumours and cell lines in the absence of somatic activating mutations in BRAF, RAS, GNAQ, GNA11 and KIT genes or alterations in the expression of the main components of the pathway." (PMID 25413220, 2014). "Notably, the canine oral melanomas in our series also lacked SF3B1 and GNAQ mutations, and no mutations in POLE, PTPRD, or DMXL2 were found, suggesting that these canine cancers may not represent a faithful genetic model for the subset of human mucosal melanomas with mutations in these genes." (PMID 30664638, 2019).
cardiac hypertrophy (40 papers, 2009 to 2025). "Inhibition of guanine nucleotide-binding protein subunit alpha-11, 14, and 15 (GNA-11,14,15), along with GNAQ, inhibits 1-phosphatidylinositol 4,5-bisphosphate phosphodiesterase beta-1, 2, 3, and 4, thus reducing cardiac hypertrophy through EGFR blockade." (PMID 28649439, 2017). "Gq (GNAQ) overexpression leads to heart hypertrophy and contractile failure in transgenic mice, and knockout prevents ventricular hypertrophy in response to pressure-overload." (PMID 24578694, 2014).
cutaneous melanoma (36 papers, 2012 to 2025). A primary melanoma arising from atypical melanocytes in the skin. "Uveal melanomas are the most frequent tumors of the eye and display a genomic mutational profile different from cutaneous melanomas, with GNAQ/GNA11, BAP1 and SF3B1 being the genes most frequently mutated." (PMID 39727691, 2024). "UM tumors are frequently detected with mutations in GNA11, GNAQ, EIF1AX, BAP1, and SF3B1 instead of the typical mutations associated with cutaneous melanoma." (PMID 40283643, 2025). "In this regard, GNAQ/GNA11-driven UM is similar to cutaneous melanomas that are driven by other oncogenes." (PMID 41154654, 2025). "GNAQ and GNA11 mutations are prevalent in primary CNS melanoma but differ from cutaneous melanoma (CM), in which BRAF, NRAS, KIT, and NF-1 mutations are more common." (PMID 41536409, 2025). "Acral melanomas have a higher frequency of triple-negative melanomas (45–58%) and consequently exhibit a higher frequency of KIT, GNAQ and TYRP1 mutations compared with cutaneous melanomas." (PMID 39727691, 2024). "The majority of ocular melanomas have mutations in GNAQ or GNA11, and 6% of cutaneous melanomas have also shown mutations in these genes." (PMID 34943797, 2021). "Our results suggested that oncogenic mutations in GNAQ and its closely related homolog, GNA11, are rarely found in cutaneous melanoma because the epidermal microenvironment causes Gαq/11 signaling to inhibit melanocytes." (PMID 34939927, 2021). "We validated previous reports that the commonly known mutations in cutaneous melanoma, including BRAF, NRAS, NF1, GNAQ and GNA11, were rarely mutated in mucosal melanomas." (PMID 30847022, 2019). "The majority of human cutaneous melanomas are driven in part by constitutive activation of the MAPK pathway through mutation of genes such as BRAF, NRAS, NF1, KIT, GNAQ, and GNA11, often in a mutually exclusive pattern." (PMID 30188888, 2018). "Although GNAQ and GNA11 mutations have been reported in a cutaneous melanoma case and a cell line from cutaneous melanoma, there are no data to demonstrate GNAQ or GNA11 mutations in mucosal melanoma." (PMID 25030020, 2014). "Our panel also included five cutaneous melanoma cell lines wild type for mutations in NRAS, BRAF, GNAQ and GNA11 and only one was highly sensitive to TAK733 with IC50s below 1 nM, while two were considered sensitive with IC50 less than 10 nM." (PMID 22515704, 2012). "It is widely recognized that, unlike cutaneous melanoma, the vast majority (>90%) of UM cases are driven by activating mutations in the GNAQ and GNA11 genes, which encode the alpha subunits of heterotrimeric G-proteins." (PMID 41154654, 2025). "Taking these results together, the approach pinpointed well-established driver genes also detected by frequency-based methods, but also likely drivers not readily detected by such methods, giving further support for GNAQ, KIT and SF3B1 driver mutations in cutaneous melanoma." (PMID 36396655, 2022). "In line with earlier observations in skin melanoma cells, these effects were independent of the mutational status (GNAQ, GNA11, BAP1, BRAF and NRAS) of the UM and CM cell lines." (PMID 34508176, 2022). "Unlike cutaneous melanoma (CM), nearly all UMs harbor a mutation in the Gαq pathway, mainly GNAQ and GNA11, both of which are α subunits of G proteins." (PMID 34885078, 2021). "As an example, GNA15 (encoding Gαq subunits) is significantly mutated in skin melanomas that do not often carry GNAQ or GNA11 mutations." (PMID 32532044, 2020). "However there is some overlap in tumor biology as ~80% of blue nevi, which are benign melanocytic tumors of the skin, also harbor GNAQ or GNA11 mutations, and BAP1 mutations can be found in both cutaneous nevi and cutaneous melanoma." (PMID 23694694, 2013).